IL13 (interleukin 13)
Diseases named in the same sentence as IL13 in open-access papers (continued):
Sharing a sentence is not in itself a finding about the gene and the disease.
tumor (continued). "Other studies have shown that the inflammatory-inducing effect on pancreatic tumorigenesis is mediated by the release of interleukin-13, which induces the conversion of inflammatory macrophages into alternatively activated macrophages, exhibiting tumor-promoting effects." (PMID 29156578, 2017). "Moreover, pDCs in the tumor microenvironment trigger IL-5/IL-13-secreting Th2 cells and IL-10-secreting Tregs through the expression of OX40L and ICOSL." (PMID 29085361, 2017). "For instance, the chemokine CCL2 and macrophage colony-stimulating factor were shown to recruit inflammatory monocytes to the tumour site, and then differentiate into TAMs in response to IL-4, IL-10, IL-13 and other cytokines in the tumour microenvironment and promote tumour metastasis." (PMID 29065107, 2017). "Both molecules contribute to carcinogenesis by stimulating cancer cell proliferation, inhibiting apoptosis, increasing invasiveness, and modulating inflammation and immunity through the induced release of Th2 cytokines, such as IL-10, TGF-β, IL-4, and IL-13, by TAMs and the tumor cells." (PMID 28970834, 2017). "In turn, increased IL-13 secretion by primed ILC2s results in a significant expansion of activated M-MDSCs, which may inhibit anti-tumour immune responses." (PMID 28928446, 2017). "Tumor development was associated with the appearance of F4/80+CD11bhighGr1low M2 macrophages that produced the tumor-promoting factors IL-6 and EGF, in a CD1d- and IL-13-dependent manner." (PMID 29375569, 2017). "Similarly to eosinophils, when basophilia was induced in these mice by treatment with interleukin-13, enhanced T-cell infiltration and tumor rejection resulted, indicating a similar anti-tumor role of basophils." (PMID 29099772, 2017). "IL-13 has just recently been described as a contributor to growth of tumor cells in CTCL." (PMID 27294147, 2016). "Although direct evidence is currently lacking, it hence seems likely that ILC2s contribute to tumor immune evasion via IL-13-mediated stimulation of tumor-associated myeloid cells." (PMID 28536374, 2016). "Consistent with this, mice lacking IL-13 were also more susceptible to this inflammation-driven carcinogenesis and developed significantly more and bigger tumours than WT controls." (PMID 27357235, 2016). "Furthermore, we looked at gene expression of IL-4 and IL-13, which typically promote alternative activation of macrophages into M2 cells, which is generally tumor promoting." (PMID 27827906, 2016). "Therefore, IL13-PE has the potential to generate synergistic antitumour effects, directly killing tumour cells and specifically ablating protumoural M2Mφs." (PMID 27271009, 2016). "Survival analyses assessed by Kaplan-Meier plots and log-rank tests disclosed that densities of both CD68 and IL-13 in tumor stroma were significantly positively correlated to the overall survival time and disease-free survival time of patients after operation (p < 0.0001)." (PMID 26771842, 2016). "The synergism between IL-4 and IL-13 seems to contribute to tumor cell growth." (PMID 27294147, 2016). "Therefore, it would be valuable to determine if IL-13Rα2 acts as a core factor to control the dual axes of YKL-40/IL-13Rα2 and IL-13/IL-13Rα2 in tumor malignancy." (PMID 26439689, 2015). "Co-treatment with metformin eliminated these tumor-promoting phenotype induced by IL-13." (PMID 26497364, 2015). "Taken together, the results have demonstrated that EAT growth is modulated by PGE2 and the inhibition of the tumor growth could be partly related to suppression of IL-6 and induction of IL-13." (PMID 26347589, 2015). "In conclusion, our findings showed that PGE2 modulates the growth of EAT and that inhibition of tumor growth could be partly related to suppression of the release of IL-6 and to stimulation of the release of IL-13." (PMID 26347589, 2015).
tumor (continued). "Because there are many cytokines in the tumor microenvironment, including IL-4, IL-6, IL-10, and IL-13, we next asked whether these cytokines down-regulated miR-146a and miR-222 in late tumor TAMs." (PMID 26689540, 2015). "Taken together with our observation that apoptotic cells and IL-4Rα have additive effects in promoting tumor growth (and macrophage accumulation), our results are consistent with roles for IL-4/IL-13 in driving NHL-promoting mechanisms independently of apoptosis." (PMID 25702581, 2015). "Our data was incompatible with these theories, therefore it may be important to evaluate the relationship of tumor microenvironment and IL13 signaling." (PMID 26114873, 2015). "However, M2 macrophages, activated by IL-10, IL-13, and so forth, have an immune regulating and suppressive role via multiple ways to promote tumor progression." (PMID 26161392, 2015). "We have presently analyzed inflammation-related factors in whole tumor samples, having found that the pro-inflammatory cytokine IL-1β and the anti-inflammatory cytokine IL13 expression was altered (higher and lower, respectively) in cachectic cancer patients, as compared to WSC." (PMID 26732354, 2015). "In addition, the treatment of EAT-bearing mice with indomethacin has stimulated the IL-13 production and has significantly inhibited IL-6 in the 13th day of tumor growth." (PMID 26347589, 2015). "We evaluated whether the classical signaling pathways of IFN-γ (STAT1) and IL-13 (STAT6) were activated in tumor cells following culture in activated lymphocyte-conditioned medium." (PMID 24911872, 2014). "The presence of IL13 and M-CSF in cHL cases might be responsible for the induction of MΦ-2-like CD163+ tumor-associated macrophages in cHL, whereas IL4 was detected infrequently and, if at all, seems to play a minor role." (PMID 25470820, 2014). "Moreover in mice, adoptive transfer of IL13-zetakine T cells display potent anti-tumor activity against established IL13Rα2pos PBT017-4 and PBT030-2 xenografts which express a mesenchymal gene expression profile." (PMID 24204956, 2013). "Lack of IL-13 did not abrogate the effect of absence of IL-4Rα-mediated signalling in DKO animals, thereby refuting the hypothesis that increased tumour initiation in IL-4Rα−/− mice is dependent on IL-13 signalling." (PMID 23784081, 2013). "The subsequent secretion of type 2 cytokines such as IL-4 and IL-13 may actually serve to accelerate tumor growth and prevent tumor cell apoptosis." (PMID 23606870, 2013). "To examine the mechanism of antitumor response by IL-13-PE, we investigated whether treatment affected immunosurveillance to subsequently allow for enhanced tumor destruction by the immune system." (PMID 23421960, 2013). "Along with delaying tumor formation, we were able to see in the immunocompetent Tgfbr1/Pten 2cKO mice that the IL-13-PE treatment could additionally limit the development of an immunosuppressive tumor environment." (PMID 23421960, 2013). "Because IL-13 can negatively regulate anti-tumour immunity modulating NKT cell function, it may cooperate in cancer development." (PMID 23176085, 2012). "In other studies, the investigators observed that IL-4 and IL-13 can inhibit the tumor regression." (PMID 23108822, 2012). "However, when TSA or SAHA were combined with IL13-PE a dramatic inhibition of tumor growth was observed." (PMID 21477288, 2011). "Blocking OX40L in a humanized mouse model controlled tumor development and was associated with the lack of IL-13-producing T cells within the tumor." (PMID 21281484, 2011). "Because tumor cells produce various anti-inflammatory cytokines and growth factors, such as IL-6, IL-10, IL-13, VEGF, and M-CSF, OSCC-derived immunosuppressive cytokines may modulate infiltrating TAMs, leading to the M2 phenotype." (PMID 24213108, 2011). "However, when mice were treated with SAHA followed by IL-13-PE, a significant decrease in tumor size was observed." (PMID 21477288, 2011).
tumor (continued). "A high proportion of the tumor-infiltrating CD4+ T cells from this model produce IL-13 and IFNγ." (PMID 21281484, 2011). "The role of IL-13 in regulating tumor growth depends on the tumor cell type." (PMID 21991346, 2011). "As opposed to classically activated macrophages (M1), which have tumoricidal activity and elicit tissue-destructive reactions, TAMs undergo alternative (M2) activation in response to IL-4 or IL-13 that is oriented toward tissue repair, immunosuppression, and tumor promotion." (PMID 24212647, 2011). "Using a well-characterized tumor toxicity assay, we analyzed the ability of various serum samples from mice systemically sensitized to IL13-PE to block the cytotoxicity of IL13-PE against IL-13Rα2-expressing tumor cells." (PMID 20090941, 2010). "Furthermore, the suppressor functions of MDSCs and Treg cells are enhanced by IL-17-upregulated IL-10 and IL-13 in tumor microenvironment and CD39 and CD73 on Treg cells." (PMID 20111717, 2010). "Thus, IL-33 and IL-13 may not only contribute to inflammation but also create a conducive environment for tumor progression by inhibiting antitumor responses." (PMID 40761291, 2025). "Eosinophils and mast cells might inhibit Th1 anti-tumor immunity by releasing Th2 cytokines such as IL-4 and IL-13, but their metabolic pathways (such as cytochrome P450) that were highly expressed at the same time might play a protective role by clearing carcinogens." (PMID 40568599, 2025). "Additionally, high levels of IL‐13 receptors are expressed in the CRC area and precancerous polyps, indicating that MAIT cells may promote tumor development and metastasis through the IL‐13 pathway." (PMID 41179703, 2025). "However, MAIT cells, characterized by impaired Th1 cytokine production or increased IL-17 secretion, adopt an immunosuppressive phenotype within the TME, which sustains chronic inflammation and tumor growth, or enhance IL-13 expression, fostering a Th2-skewed and protumor microenvironment." (PMID 40746558, 2025). "Therefore, in this context, it is suggested that IL-13 induction might be a common mechanism of tumor resistance, with IL-13Rα2 contributing to resistance as the receptor for IL-13." (PMID 39598436, 2024). "Similarly, IL-13 plays a role in anti-tumour immune responses; however, it may inhibit anti-tumour immunity by suppressing IFN-γ secretion, which promotes Th1 responses and CD8+ cytotoxic T lymphocyte activity." (PMID 38673958, 2024). "Furthermore, treating THP‐1 cells with PMA + IL‐4 + IL‐13 for 72 h resulted in a decrease in Wnt5a protein expression in HCT116 cells, which may be associated with its involvement in tumor cell differentiation‐related functions." (PMID 39302044, 2024). "However, recent studies have demonstrated a specific and nonredundant role for IL-13 in host immunity against parasites, inflammatory airway susceptibility, and tumor progression." (PMID 38607023, 2024). "Importantly, in vitro antibody-mediated neutralisation of ILC2-derived IL-4 and IL-13 reduced tumour MDSC Arg1 levels, and similarly genetic deletion of IL-13 in mice with CRC decreased Arg1+ MDSCs, increased IFNγ production by Th1 cells and CD8+ T cells, and significantly reduced tumour burden." (PMID 38464388, 2024). "However, the expression levels of typical anti-inflammatory cytokines, Il4, Il10, and Il13, which are predominantly produced by tumor-associated macrophages (TAM) in the tumor microenvironment (TME), were similar between the control and creatine-supplemented groups." (PMID 37662917, 2023). "Similarly, IL-13 largely inhibits tumor cell growth, but recent studies revealed that it could promote the survival of certain tumors through suppression of immunosurveillance." (PMID 38003396, 2023). "However, it could be considered as evidence for slowing tumor growth through T-cell-mediated immunosurveillance; yet, the blockade of IL-13 further enhanced this effect, which confirmed a role for the type 2 immune response in promoting tumor growth." (PMID 37835465, 2023).
tumor (continued). "In addition to directly killing tumour cells, IL-13Rα2-targeting CAR-T cells may eliminate other IL-13-responsive cells in the tumour microenvironment contributing to therapeutic efficacy." (PMID 37455828, 2023). "Collectively, these studies suggest that IL-25-mediated activation of ILC2s, and IL-33-mediated stimulation of Th2 cells, may act as independent parallel pathways to induce the production of IL-4 and IL-13 leading to the activation of MDSCs to suppress anti-tumour T cells and promote CRC." (PMID 36263033, 2022). "M2 macrophage behaviour exists more heterogeneously and can be triggered by IL-4 or IL-13, IL1-β, TGF-β, IL-6, phagocytosis of apoptotic cells, or association with a tumour microenvironment, respectively, generating M2a, M2b, M2c, M2f, and tumour-associated macrophages (TAM)." (PMID 36254592, 2022). "Moreover, unlike IL-5, IL-13-producing ILC2s had been associated to poor prognosis in breast cancer through immune suppression limiting anti-tumour T cell responses." (PMID 35406451, 2022). "On the other hand, the M2 phenotype secretes cytokines such as IL-4, IL-13, IL-10, vitamin D3, and glucocorticoids, which leads to weakening of the antitumor activity and an enhancement of the ability to support angiogenesis and tissue remodeling, which is beneficial for tumor growth and invasion." (PMID 36611344, 2022). "Awaji found that KRAS mutation could promote the secretion of paracrine factors such as IL4, IL10, and IL13 in tumor cells and simultaneously activate CXCR2 signaling in CAFs, resulting in the formation of a secreted CAF phenotype by activating NF-κB signaling and promoting tumor progression." (PMID 36076911, 2022). "Moreover, the finding that combined blockade of PD-L1 and IL10 further enhanced T-cell immunity 50, 51 suggests that IL13 may also have the potential to be targeted together with PD-1/PD-L1 to increase anti-tumor function." (PMID 33754038, 2021). "RORα-deficient mice would also have reduced IL-13 production due to the absence of ILC2s but it is not known whether this has also contributed to the increase in tumour burden." (PMID 33535624, 2021). "Interestingly, the frequency of IL-5- and IL-13-expressing ILC2s and IL-17A-producing ILC3s were positively correlated with tumour burden, suggesting that CAC development may be augmented by the local accumulation of these cytokines in the colon." (PMID 33535624, 2021). "In addition, tumors have been found to induce production of type II NKT cells, which in turn secrets IL-13, thereby not only causing aggregation of MDSC in the tumor microenvironment but also activating the STAT6 signaling pathway and suppressing CD8+ T cell function." (PMID 35111740, 2021). "In this study, we hypothesized that the HMC3 cells, upon stimulation with anti-inflammatory cytokines (IL-4, IL-13, IL-10, TGFβ, CCL2) released from cancer cells, will show an increased expression of immuno-suppressive and tumor-supportive proteins and associated pathways." (PMID 34566949, 2021). "Moreover, the crucial roles of IL-13 have been studied in tumors as it was reported that IL-13 was over expressed in tumor tissues and targeting IL-13 in cancer may have a potent role in cancer immunotherapy." (PMID 34696438, 2021). "CCL2, CCL3, TIMP-1, and IL-13 are products readily found in an immune response that is driven by M2 macrophages, which correspond to a tumour growth-promoting phenotype that aids tumour cell proliferation, reduction of an antigen-specific immune responses, and increased angiogenesis." (PMID 33494138, 2021). "Tumor cells may secrete factors to promote Th2 and TAM2 (Tumor-Associated Macrophage) polarization, which in turn amplify this type of inflammation via IL-4, IL-5 and IL-13, suppress anti-tumor Th1 polarization and responses, and correlate with MDSC infiltrates." (PMID 33498483, 2021).
tumor (continued). "In supernatants derived from RANK+/+ tumor acini, many cytokines were upregulated including stromal cell-derived factor-1α, macrophage inflammatory protein-1α, interleukin (IL)-1α, stem cell factor, tumor necrosis factor-α, IL-13, macrophage colony-stimulating factor, IL-10, IL-4, IL-17, and IL-1β." (PMID 33303745, 2020). "These cell types have previously been shown to either promote or hinder anti-tumor immunity depending on their cytokine production profile, with type I NKTs producing IFNγ to recruit NK cells and activate DCs, whereas Type II NKTs produce IL-13 and TGF-β that suppress anti-tumor immunity." (PMID 33339195, 2020). "T cells co-expressing HER2 and IL13-Rα2 CARs could effectively target and kill tumor cells that express either HER2 or IL13-Rα2, and showed particularly enhanced anti-tumor activity and antigen-dependent downstream signals compared with a single targeting strategy." (PMID 33224149, 2020). "Consequently, both tumor promoting and protective roles have been advocated for IL-4 and IL-13." (PMID 32512917, 2020). "However, the effect of over-expression of IL-13 may alter in different tumor types and in some instances its secretion can enhance tumor growth." (PMID 33008336, 2020). "In addition, IL-13 from ILC2s plays a critical role in recruiting myeloid-derived suppressor cells (MDSCs) and M2 phenotype macrophages, which establish an immunosuppressive microenvironment to restrain anti-tumor responses." (PMID 31354745, 2019). "Interestingly, it was demonstrated in pancreatic tumors that a complex interaction between mast cells and stellate cells (often described as CAF precursors) is able to activate mast cells, which in turn enhance CAF proliferation by their secretion of IL-13 and tryptase, favoring tumor growth." (PMID 29545811, 2018). "Alternatively, IL-4 and IL-13 produced by Th2 cells induce macrophage polarization towards the M2 phenotype; M2 macrophages secretes anti-inflammatory cytokines such as IL-10, immunosuppressive factors, and tumor growth factors, which promote tumor cell growth and metastasis." (PMID 29707119, 2018). "Moreover, Th2 cells' interaction with the TME and particularly with MSCs inhibits immune rejection of the tumor (through the production of Interleukin-4, IL-4, Interleukin-5, IL-5, and Interleukin-13, IL-13) and promotes the presence of immunosuppressive type 2 macrophages." (PMID 28473858, 2017). "The tumour-protective effect of IL-13 additionally appears to be restricted to carcinogenesis at the epithelial skin barrier, as mice lacking IL-13 were not more susceptible to subcutaneous tumour growth." (PMID 27357235, 2016). "This is specific to IL-13 as mice lacking IL-4 were significantly less susceptible to tumour development following DMBA–TPA, suggesting that IL-4 may drive inflammation in this model, whereas IL-13 works differently." (PMID 27357235, 2016). "Indeed, experiments in an orthotopic mouse model of pancreatic cancer suggest that IL-13Rα2 is an important mediator of the pro-tumor effects of IL-13, including activation of AP-1 growth signals, production of immunomodulatory cytokines such as TGF-β, and promotion of metastasis." (PMID 24672527, 2014). "We observed that IL-13-PE could significantly decrease tumor size in both IL-13Rα2-positive tumors." (PMID 21477288, 2011). "Furthermore, STAT6--a signal transducer downstream in the IL-13 receptor signaling pathway--is phosphorylated, suggesting the IL-13 from infiltrating CD4+ T cells in the tumor microenvironment may contribute to tumor development." (PMID 21281484, 2011). "In addition, the levels of IL-10 and IL-13 were also increased in tumor after BMMC injection." (PMID 20111717, 2010). "To determine whether VEGFR-2 expression on pCSCs is regulated by tumor environmental cues, we examined the effects of cytokines on the expression in vitro., including Flt3 ligand (FL), GM-CSF, IL-3, IL-4, IL-6, IL-7 and IL-13." (PMID 18286204, 2008).